TNKS (tankyrase)
Diseases named in the same sentence as TNKS in open-access papers (continued):
Sharing a sentence is not in itself a finding about the gene and the disease.
cancer (continued). "Tankyrase 1 (TNKS1) and tankyrase 2 (TNKS2) are two homologous proteins that are gaining increasing importance due to their implication in multiple pathways and diseases such as cancer." (PMID 33910596, 2021). "However, only five similar proteins were identified in all three cancer cell lines and these include SSSCA1 as expected, Tankyrase 1 (TNKS1), γ-tubulin (TUBG1), and the poorly characterized rRNA methyltransferase MRM2 and membrane associated VAPA." (PMID 32170109, 2020). "Additionally, these results demonstrate that in vivo therapeutic benefit for the combination of MEK and TNKS inhibition in KRAS and PIK3CA mt cancers." (PMID 30944457, 2019). "TNKS inhibitors provide an opportunity to suppress hyperactive WNT signaling in tumors, however, they have shown limited anti-proliferative activity as a monotherapy in human cancer cell lines." (PMID 31891587, 2019). "In conclusion, the characterization of tankyrase-mediated cellular processes, especially the AXIN-regulated pathway, has resulted in advances in preclinical research on the utility of tankyrase inhibitors for treating cancers and fibrotic diseases." (PMID 30813388, 2019). "Whereas the role of RAB11FIP1 in cancer is not as clear, Tankyrase-1-binding protein (TNKS1BP1) binds Tankyrase, which in turn, associates with TRF1 protein at the telomeres." (PMID 26388441, 2015). "The protein levels of TNKS and KDM6A were upregulated in tumor tissues compared to those in adjacent normal tissues, suggesting that these proteins could be promising targets for cancer treatment." (PMID 40860181, 2025). "We next assessed the effects of the selective inhibitors of Wnt/β-catenin signaling, including XAV-939 (a potent tankyrase inhibitor that targets Wnt/β-catenin signaling) and Wnt-C59 (a potent porcupine inhibitor), on the upregulation of PD-L1 in BMFs induced by CMT167 or MC38 cancer cells." (PMID 33790893, 2021). "Other structurally different inhibitors have also been reported to impair WNT signaling in vitro by targeting tankyrase, including IWR-1/2, JW74/55, WIKI4, G007-LK, with some validated for anti-tumor efficacy in xenograft and/or genetically engineered mouse models of cancer." (PMID 32268564, 2020). "However, it is unknown whether the NAD+ level has an impact on increasing Axin protein level by TNKS inhibition in cancer cells and whether it is sufficient to impact cancer proliferation in the APC-mutant cancer setting." (PMID 32005247, 2020). "It is important to note that all of the work reported here has been performed in cancer cell lines in vitro, and it is not known whether the senescence phenotypes induced by combined TNKS/CDK4 inhibition will behave similarly in vivo." (PMID 31891587, 2019). "In addition to XAV939, other tankyrase inhibitors G244-LM (XAV939 analog) and G007-LK also showed anti-cancer effects in the colony-forming assay or xenograft models of APC-mutant CRC cells, despite a lack of significant effect on the viability of 2D-cultured cells." (PMID 30185973, 2018). "Importantly, tankyrase, the poly(ADP-ribose) polymerase (PARP) that catalyzes TRF1 PARsylation and releases TRF1 from telomeres, is an emerging target for cancer therapy, and PARP inhibitors are in clinical trials for the treatment of cancer." (PMID 27123041, 2013). "Hence, while TNKS inhibitors may not always provide significant anti-cancer responses as single agents, they may prove effective as part of specific treatment combinations, such as those described here and elsewhere." (PMID 31891587, 2019).
tumor (70 papers, 2009 to 2026). "In summary, combined anti-PD-1/G007-LK treatment of B16-F10 tumors is dependent on tankyrase inhibitor-mediated loss of β-catenin in the tumor and induces an IFNγ and CD8+ T cell-dependent growth-inhibitory effect." (PMID 32332858, 2020). "However, in most cases, high doses of tankyrase inhibitors required to suppress tumor growth often result in intestinal toxicity, weight loss and even death in rodents." (PMID 32268564, 2020). "Furthermore, the elevated doses of tankyrase inhibitors required to elicit tumour inhibition often result in intestinal toxicity, weight loss and death in rodents." (PMID 30655555, 2019). "Unravelling the mechanisms underlying tumor response to tankyrase inhibition will yield a better understanding of whether WNT signaling or other tankyrase interactions are responsible for tumor growth inhibition in CRC." (PMID 27070088, 2016). "Here, we show that the dual PARP/tankyrase (TNKS) inhibitor JPI-547 exerts potent antitumor activity, particularly in PTEN-deficient Ishikawa tumours." (PMID 42286682, 2026). "Overexpression of LASS2 combined with a tankyrase inhibitor (XAV939) synergistically inhibits tumor growth and restores cisplatin sensitivity." (PMID 38191448, 2024). "The impact of targeting TNKS on cell growth, invasion, apoptosis, key genes and signalling pathways was investigated in tumour cells by Western blotting, rescue experiments, colony formation assays, flow cytometry and label‐free experiments." (PMID 38898581, 2024). "We found that TNKS high expression was closely related to the advanced tumour stage and tumour size in lung adenocarcinom." (PMID 38898581, 2024). "This study uncovers the effectiveness and therapeutic window for a novel tankyrase inhibitor in mouse tumor models." (PMID 36873622, 2022). "Small-molecule tankyrase 1 and tankyrase 2 (TNKS1/2) inhibitors are effective antitumor agents in selected tumor cell lines and mouse models." (PMID 34337362, 2021). "A similar role for AMOT was described in PSC neural commitment, while inhibitors of Tankyrase have been recently proposed to negatively regulate YAP by stabilizing AMOT in tumor cells." (PMID 33116297, 2021). "G007-LK, one of the most characterized TNKS inhibitors, was found to exhibit a strong tumor growth inhibition in colon xenograft mouse models." (PMID 33910596, 2021). "The use of model systems with defined and traceable anti-tumor CD8+ T cell specificities would also be of value in determining the effects of tankyrase inhibition on the kinetics and qualitative characteristics of the ensuing immune response." (PMID 32332858, 2020). "Third strategy to augment anti-tumor immune responses involves promoting β-catenin degradation using TNKS inhibitors." (PMID 32132993, 2020). "Recent studies have shown that treatment of melanoma or EG7 tumor-bearing mice with TNKS inhibitors XAV939 or JW55 markedly delayed tumor growth with augmented anti-tumor immunity." (PMID 32132993, 2020). "Serial sections and immunohistochemical (IHC) staining showed that tumor tissues injected with circ5615 ASO had fewer TNKS, β-catenin, and CCND1-positive cells." (PMID 32393760, 2020). "Crucially, application of therapeutic ASO targeting circ5615 significantly reduced tumor volume with the effect on Wnt signal pathway, providing new insight into TNKS-suppressive therapy." (PMID 32393760, 2020). "On the other hand, a tankyrase inhibitor show both anti-tumor and antidiabetic effects via activating the AMPK pathway." (PMID 31554794, 2019). "Whilst tankyrase catalytic inhibitors can suppress tumour cell growth, in-vivo studies have also pointed to different degrees of tankyrase-inhibitor-induced intestinal toxicity in mice." (PMID 31836723, 2019). "Inhibition of the PARP superfamily tankyrase enzymes suppresses Wnt/β-catenin signalling in tumour cells." (PMID 30655555, 2019).
tumor (continued). "Here we perform a domain-focused kinome CRISPR library screen, aiming to identify the most critical mitogenic signaling components that mediate resistance to TNKS inhibition, with the goal of defining combination approaches to enhance tumor cell response." (PMID 31891587, 2019). "The results showed that TNKS knockdown led to slower growth rate and lighter tumor weight compared with the control group." (PMID 30915350, 2019). "As Tankyrase inhibitors have been shown to suppress tumor cell growth via inhibiting YAP, we investigated the effect of two Tankyrase inhibitors, XAV-939 and G007-LK, in regulating HCC cell growth." (PMID 28877210, 2017). "For instance, the tankyrase inhibitor G007-LK was shown to have anti-tumor effects in 2 out of 4 CRC cell lines." (PMID 27070088, 2016). "More recently, the tankyrase inhibitor NVP-TNKS656 was shown to significantly inhibit tumor growth in 1 out of 3 CRC PDTX models." (PMID 27070088, 2016). "All of these results argue that the growth inhibitory effects of XAV939 in Hippo pathway mutant tumor cells were primarily due to its inhibition of TNKS-mediated angiomotin degradation." (PMID 27144834, 2016). "Of these, only G007-LK was reported to inhibit tumor growth as a single agent in certain models, while the majority of tankyrase inhibitors lack antitumor activity in vivo." (PMID 26513298, 2015). "The molecular basis for the anti-tumor activity of SMA involves increased activity of the β-catenin destruction complex through the inhibition of tankyrase and PI3K/Akt pathway." (PMID 26544726, 2015). "However, emerging evidence suggests that lower doses of TNKS inhibitors, when incorporated into combination therapy regimens, can achieve notable anti-tumor efficacy." (PMID 40180907, 2025). "Importantly, treatment of A549 cells with the tankyrase inhibitor significantly sensitized these tumor cells to thapsigargin-induced caspase-8 processing and apoptosis." (PMID 39904986, 2025). "In addition, inhibitors targeting TNKS are being explored as potential therapies strategy to suppress tumor growth driven by aberrant Wnt/β-catenin signaling 66-68." (PMID 40860181, 2025). "Furthermore, the tankyrase inhibitor XAV939 has been shown to reduce YAP/TEAD activity in different tumor cell lines by translocating YAP from the nucleus into the cytoplasm." (PMID 39904986, 2025). "Regarding antitumor activity of tankyrase inhibitors, especially its effect on the (tumor) vasculature deserves careful consideration as any systemic application of tankyrase inhibitors would come directly in contact with and pass the endothelial cells (EC) lining the vasculature." (PMID 37741944, 2024). "Immunohistochemistry was used to analyse TNKS expression in tumour tissues." (PMID 38898581, 2024). "The present study is devoted to the analysis of transcriptome profiles of tumor cells in the development of resistance to docetaxel as well as to the assessment of the combined effect with the XAV939 tankyrase inhibitor on maintaining the sensitivity of tumor cells to chemotherapy." (PMID 36361635, 2022). "In addition, it will be necessary in the future to deepen the knowledge of the TNKS interactoma in normal and tumor cells to define and identify new TNKS substrates." (PMID 33910596, 2021). "Our results provide evidence that the anti-tumor effect of combined tankyrase and checkpoint inhibitor treatment against B16-F10 tumors is dependent on both IFNγ and CD8+ T cells and occurs, at least in part, through direct suppression of WNT/β-catenin signaling within the tumor cells." (PMID 32332858, 2020). "The development of TNKS inhibitors has received focus because of their potential as a possible anticancer treatment strategy, and chemical TNKS inhibition has been shown to impact a number of tumor models." (PMID 32575464, 2020).
tumor (continued). "However, in most cases, when used as single agents (i.e. not in combination regimens), even when at relatively high-concentrations, tankyrase inhibitors appear to only partially impair tumour growth." (PMID 30655555, 2019). "However, tankyrase inhibitor G007-LK had a substantial tumor-suppressive effect primarily on LKR13 tumors and much less so on LKR13-LKB1-ko tumors." (PMID 31554794, 2019). "This suggests that inhibition of parallel mitogenic signals may synergize with TNKS inhibitors to control tumor cell growth." (PMID 31891587, 2019). "Based on the herein presented in vivo lineage tracing data and morphological characterisation we conclude that doses of the tankyrase inhibitor G007-LK shown to be sufficient to inhibit tumour growth are well tolerated by mice within the time frames investigated." (PMID 29316982, 2018). "However, the anti-tumor effects observed in this study were likely a result of alternative tankyrase effects whereby tankyrase inhibition reduced NuMA levels." (PMID 27070088, 2016). "One possible explanation could be that another ubiquitin ligase(s) acts independently of TNKS, to preferentially inhibit angiomotin accumulation in the resistant tumor cells." (PMID 27144834, 2016). "Efforts aimed at developing TNKS inhibitors to target Wnt activated tumors have recently led to new compounds with better drug-like properties compared to XAV939 with evidence of some efficacy in Wnt tumor models." (PMID 27144834, 2016). "Rather, it may be necessary to use tankyrase inhibitors in combination with other pathway specific compounds to effectively attenuate tumor growth." (PMID 23144924, 2012). "Exposure to RDX also induced aberrant expressions of other onco-miRNAs and tumor-suppressing miRNAs, such as let-7, miR-10b, miR-15, miR-16, miR-26 and miR-181, which regulated tumor pathogenesis or genes related to the cell cycle (e.g., TNKS)." (PMID 21592377, 2011). "Biomolecular condensation might play a role in tumor cells where TNKS are overexpressed." (PMID 33923443, 2021). "Mechanistically, we demonstrate that the synergistic effect of tankyrase and checkpoint inhibitor treatment is dependent on loss of β-catenin in the tumor cells, anti-PD-1-stimulated infiltration of T cells into the tumor and induction of an IFNγ- and CD8+ T cell-mediated anti-tumor immune response." (PMID 32332858, 2020). "Indeed, blocking MEK, PI3K, or EGFR can enhance the anti-tumor effect of TNKS inhibitors." (PMID 31891587, 2019). "This suggests that the use of tankyrase inhibitors in appropriate combination treatment regimens might be more appropriate as these might allow reduced doses of tankyrase inhibitors to elicit anti-tumour responses or even enhance the anti-tumour effects of additional agents." (PMID 30655555, 2019). "Furthermore, overexpression of tankyrase in several tumour types has been reported and may accentuate tankyrase's concentration‐dependent scaffolding functions, contributing to TNKSi resistance." (PMID 28910490, 2017). "In our study, we were able to observe anti-tumor effects under optimal serum conditions; however, in vitro anti-proliferative effects were only modest, also suggesting that combination therapy or a more potent tankyrase inhibitor may be necessary." (PMID 26246473, 2015). "Losses in the 8p23.1 region, which contains multiple genes related to immune function, T-cell regulation (TNKS, PPP2CB,) and tumor suppression (CSMD1, MSR), were enriched in MEITL (61% versus 7%, p = 0.02)." (PMID 41057685, 2026). "Consistent with the changes in protein levels, TNKS and KDM6A mRNA levels were reduced in all CisR tumor spheroids following CREB knockdown combined with cisplatin treatment." (PMID 40860181, 2025). "In contrast, CisR tumor spheroids maintained the expression of CREB and its downstream targets TNKS and KDM6A, as well as cell survival in response to cisplatin." (PMID 40860181, 2025).
tumor (continued). "Knockdown of TNKS and KDM6A sensitized CisR A549, H1299, and H358 tumor spheroids to cisplatin, resulting in reduced cell viability and increased levels of cleaved caspase-7." (PMID 40860181, 2025). "Inhibition of tankyrase by XAV.939 stabilizes the transcriptional co-activator protein YAP/TAZ, leading to enhanced Hippo pathway signaling and subsequent tumor suppression." (PMID 37251938, 2023). "JW55 inhibiting PARP domain of tankyrase 1 and tankyrase 2, as well as JW67 and JW74 which suppress tumor growth in Apc mutant mice, have been introduced as drug candidates too." (PMID 33224221, 2020). "Combined treatment with a WNT/tankyrase inhibitor reduced nuclear β-catenin, reverted resistance to PI3K and AKT inhibitors, and repressed tumor growth." (PMID 28476164, 2017). "Tankyrase inhibition has been shown to revert resistance to PI3K and AKT inhibitors in colorectal cancer patient-derived sphere cultures and mouse tumor xenografts." (PMID 28476164, 2017). "All of these results strongly argued that XAV939 functions through TNKS inhibition to specifically downregulate TEAD transcriptional activity and inhibit the proliferation of Hippo mutant tumor cells." (PMID 27144834, 2016). "In the current study, we investigated the anti-tumor efficacy of XAV939 and a novel nitro-substituted derivative (WXL-8), in both in vitro and in vivo models of HCC, and demonstrated that tankyrase inhibition is a feasible approach in the treatment of HCC." (PMID 26246473, 2015). "We evaluate TNKS enzymes as potential therapeutic targets in HCC, and the anti-tumor efficacy of tankyrase inhibitors (XAV939, and its novel nitro-substituted derivative WXL-8) in HCC cells." (PMID 26246473, 2015). "Moreover, in CisS tumor spheroids, cisplatin treatment substantially decreased the expression of CREB mRNA and protein, and decreased the levels of TNKS and KDM6A proteins, resulting in a substantial increase in apoptotic cell death." (PMID 40860181, 2025). "Furthermore, CREB knockdown led to increased sensitivity to cisplatin with reduced levels of TNKS and KDM6A in both cisplatin-resistant tumor spheroids and tumors in a xenograft mouse model." (PMID 40860181, 2025). "However, Tankyrases (TNKS1 and TNKS2) are a group of enzymes involved in the Wnt signaling pathway that play a crucial role in tumor cell growth and development, including CRC." (PMID 40943055, 2025). "Tankyrase 1 (TNKS1) is a key regulator of this pathway, promoting the stabilization of β-catenin, which translocates to the nucleus and activates transcription factors that drive tumor growth." (PMID 40699862, 2025). "TNKS inhibitors can control WNT hyperactivation and provide long‐term tumour control in vivo." (PMID 38898581, 2024). "The tankyrase inhibitor XAV939 could reduce the expression of β‐catenin by upregulating AXIN1, increase apoptosis induced by 5‐Fu and suppress tumor growth in CRC." (PMID 38419282, 2024). "Wnt–β-catenin signaling is blocked by various TNKS inhibitors such as tankyrase inhibitor 49 (TNKSi49), XAV939, JW74, AZ1366, IWR-1, NVP-TNKS656, WIKI4, G007-LK, and JW55 in different tumor models." (PMID 31684152, 2019). "Notably, tankyrase inhibitors also induced LKB1-AMPK activation, tumor suppression and reduced blood glucose levels in diabetic mice." (PMID 31554794, 2019). "Despite their ability to dampen hyperactive WNT and suppress tumor growth in model systems, TNKS inhibitors do not always show anti-proliferative effects as single agents in human CRC cell lines." (PMID 31891587, 2019). "Our findings that TNKS inhibitors predominately induced G1 arrest rather than cell death in Hippo pathway mutant tumor cells have potential parallels with the G1 arrest induced by tyrosine kinase pathway inhibitors in solid tumor cells." (PMID 27144834, 2016). "All of these findings establish that TNKS inhibitors antagonize Hippo pathway mutant tumor cells primarily through angiomotin stabilization independent of other TNKS functions." (PMID 27144834, 2016).
tumor (continued). "Pharmacologic inhibition of Wnt ligand signaling with the porcupine inhibitor LGK-974 or of degradation of destruction complex components with the tankyrase inhibitor G007-LK in three CAC PDXs (two Wnt wild-type, one APC-mutant) did not suppress tumor growth." (PMID 36611031, 2023). "Given that AZ1366 inhibits tankyrase activity but does not modulate downstream WNT signalling in this study, we set out to examine alternative mechanisms of action to explain the tumor growth inhibition of AZ1366." (PMID 27070088, 2016).